WNT5A (Wnt family member 5A)
Diseases named in the same sentence as WNT5A in open-access papers (continued):
Sharing a sentence is not in itself a finding about the gene and the disease.
breast carcinoma (continued). "Our results demonstrated that WNT5A signaling causes a reduced production of lactate in breast cancer cells in parallel with reduced cellular migration and down-regulation of PFKP." (PMID 29069720, 2017). "Elevated expression of protein inhibitor of activated STAT 1 (PIAS1) is found in breast cancer tissues and it has been shown to associate with methylated regions of WNT-5A promoter in breast cancer cells." (PMID 26514730, 2016). "The loss of WNT5A signaling plays an important role in breast cancer progression, thereby making WNT5A a tumor suppressor." (PMID 27623766, 2016). "The current literature on WNT5A expression in breast cancer strongly advocates its role as an oncosuppressor, and the loss of WNT5A expression is one of the causes of increased breast cancer progression." (PMID 27623766, 2016). "In human breast cancer, for example, loss of Wnt5a expression correlates with poor prognosis, suggesting that the gene acts as a tumor suppressor." (PMID 25019931, 2014). "Conclusively, our results suggest that loss of Wnt-5a is a valuable prognostic marker in premenopausal breast cancer patients in particular in patients with ER-positive tumors and out-performed conventional prognostic factors in this subset of patients." (PMID 23990917, 2013). "Recent studies suggest that WNT5A plays a critical role in malignant progression although loss of WNT5A protein has been linked with poor prognosis in breast cancer and correlated with the loss of ER expression." (PMID 23861811, 2013). "Although WNT5A is known to inhibit migration in breast cancer cell lines, the consequences of WNT5A expression on specific migration associated gene targets are not known." (PMID 23484019, 2013). "In a different cohort of patients, low expression of WNT‐5A protein in breast carcinomas was associated with reduced overall survival." (PMID 23727359, 2013). "We can thus suggest a link between gain-of-function mutation in PIK3CA, up-regulation of WNT5A and favorable outcome in breast cancer." (PMID 21209903, 2010). "Increased expression of Wnt-5a, a hallmark of oncogenesis, was identified in melanoma skin cancer, breast cancer cells, gastric cancer, pancreatic cancer, non-small-cell lung cancer and prostate cancer." (PMID 19603030, 2009). "In breast cancer cells, the loss of Wnt5a signaling resulted in stabilization of nuclear beta-catenin and expression of Wnt/beta-catenin target genes." (PMID 19849855, 2009). "Wnt-5a (gene L20861) has been shown to influence the metastatic behavior of human breast cancer cells, and the loss of Wnt-5a expression is associated with metastatic disease." (PMID 17316436, 2007). "A highlighted downregulated DE-gene is WNT5A which in normal tissue belongs to Wnt/β-catenin-independent signaling, binding to different receptors to promote normal development in breast tissue; its loss plays an important role in breast cancer progression." (PMID 37987362, 2023). "Notably, several studies reported that Wnt5a was highly expressed in breast stromal cells and associated with poor prognosis in breast cancer." (PMID 33754039, 2021). "However, in breast cancers, relatively few studies have examined the association between Wnt5a and drug sensitivity." (PMID 34047951, 2021). "In further support to the tumor suppressor effects and decreased expression of Wnt5a in breast cancer, it has been implicated that loss of Wnt5a expression directly correlates with advancing TNM, decreasing survival and triple-negative status in both sporadic and heredity breast cancer tissues." (PMID 34603445, 2021). "In addition, GLIS1, a novel hypoxia-inducible transcription factor, was reported to increase the migration and invasion capacities of breast cancer cells by upregulating Wnt5a, and Wnt5a levels were associated with poorer prognosis in breast cancer patients." (PMID 33754039, 2021).
breast carcinoma (continued). "However, when it comes to WNT5A expression in tumor-associated macrophages residing in breast cancer tissue and how it relates to prognosis, very little, if any, information is available." (PMID 30171384, 2018). "However, to date, no study has described the mechanism underlying malignant transformation by Wnt5a in breast cancer." (PMID 29765514, 2018). "However, in breast cancer, loss of WNT5A expression and signaling was associated with a reduced level of membranous β-catenin, suggesting that decreased cell-cell adhesion and increased migration contribute to metastatic disease." (PMID 30171384, 2018). "Interestingly, both Ror1 and Ror2 have been suggested as receptors for Wnt5a, have been linked to breast cancer progression and their expression was previously observed in breast cancer brain metastasis." (PMID 28695110, 2017). "Interestingly, macrophages associated with primary breast cancer tissues have been shown to express WNT-5A." (PMID 26514730, 2016). "Moreover, the loss of WNT5A protein in breast cancer patients has been associated with poor prognosis, early recurrence and reduced overall survival." (PMID 27623766, 2016). "Our observations in Wnt5a-deficient mammary tumors support this notion." (PMID 27500936, 2016). "To determine if Wnt5a could affect the markers associated with basal mammary cancers, we used western blot analysis to determine the level of expression of several markers including K6, K5, K14, Sca-1, K8, and keratin 10 (K10)." (PMID 25401739, 2014). "An important role for WNT‐5A is implicated in a variety of tumors, including breast carcinoma." (PMID 23727359, 2013). "Previous finding suggested that Wnt5a released from tumor-associated macrophages could have a chemotactic effect on breast cancer cells and thereby increase metastasis." (PMID 22655072, 2012). "Furthermore, heterozygous loss of WNT5A correlated with shorter survival of breast cancer patients." (PMID 29453334, 2018). "However, contradictory effects of Wnt5a have been reported in breast cancer, in which a loss of Wnt5a expression was associated with high-histological grade, high-mitotic index, and negative expression of the estrogen and progesterone receptors in the invasive ductal breast cancer." (PMID 27895670, 2016). "Furthermore, Wnt5a was detected in tumor-associated macrophages in breast cancer biopsies." (PMID 27571105, 2016). "Moreover, Wnt5a protein can inhibit ductal proliferation in the mouse mammary gland, loss of Wnt5a confers a more aggressive mammary tumor phenotype, and there is evidence that Wnt5a can antagonize the intracellular pathway of canonical Wnt signaling in several settings." (PMID 25019931, 2014). "Although Wnt5a is implicated in breast cancer pathology, its functional mechanism remains unclear." (PMID 20507565, 2010). "Western blot validation confirmed that overexpression of LRRN1 increased Wnt5A protein levels in two breast cancer cells." (PMID 41458604, 2025). "The results indicated that Wnt5A exhibited a significant positive correlation with LRRN1 in breast cancer." (PMID 41458604, 2025). "First, we measured the ability of WNT5a to inhibit canonical WNT3a activity and, second, to induce invasiveness of luminal A breast cancer cells in an in vitro, modified Boyden chamber assay." (PMID 40165582, 2025). "Consistent with our results, IVM reduced the level of Wnt5a/b in endocrine-resistant breast cancer cells." (PMID 40569965, 2025). "As another mechanism, Wnt5a induces ROR1 to recruit cortactin to promote breast cancer cell migration and metastasis." (PMID 39905197, 2025). "Functional reporter assays revealed that both WNT5a isoforms inhibit canonical WNT signaling, and EVs produced by WNT5a‐bearing tumor cells, carrying either of the WNT5a isoforms, induced invasiveness of the luminal A breast cancer cell line MCF7." (PMID 40165582, 2025).
breast carcinoma (continued). "For instance, it has been documented that Wnt5a induces invasiveness in breast cancer cell lines by acting in tandem with the Wnt/β-catenin pathway." (PMID 39123414, 2024). "Disruption of Twist-BRD4 interaction by BET-specific inhibitors in vitro and in vivo have been shown to reduce WNT5A expression and inhibit tumorigenicity and invasion of basal-like breast cancer." (PMID 38935814, 2024). "Pathologically, SMARCD3 was reported to regulate epithelial–mesenchymal transition in breast cancer by inducing WNT5A signalling." (PMID 36849558, 2023). "Because MDA-MB-231 breast cancer cells are an established cell culture system used to study responses to PCP ligands, such as Wnt5a, we examined the consequences of OTULIN loss on Wnt5a responses in these cells." (PMID 37589075, 2023). "We determined that Wnt5a-mediated migration is ablated in VANGL2 knockdown breast cancer cells, demonstrating that Wnt5a specifically activates Vangl-dependent Wnt/PCP signaling in breast cancer cells." (PMID 37147680, 2023). "In the human MDA-MB-231 breast cancer cell model, OTULIN loss caused deficits in Wnt5a-induced filopodia extension and trafficking of transfected HA-VANGL2." (PMID 37589075, 2023). "Stimulation of breast cancer cell lines with Wnt5a-conditioned media enhances cellular migration and robustly increases phosphorylation of Dvl2 compared to vector control-conditioned media." (PMID 37147680, 2023). "Vangl1 and Vangl2 knockdown and overexpression and Wnt5a stimulation were employed to manipulate Wnt/PCP signaling in a battery of breast cancer cell lines representing all breast cancer subtypes, and in tumor organoids from MMTV-PyMT mice." (PMID 37147680, 2023). "The expression level of WNT5a is elevated in some cancers and exerts as an oncogene, such as breast cancer, pancreatic cancer, prostate cancer, and gastric cancer." (PMID 37486552, 2023). "To evaluate the aggressive behavior of breast cancer cells in the presence of bone, we quantified their Wnt-5A and β-catenin levels." (PMID 40226410, 2023). "The breast cancer‐derived 5a‐D‐Luc‐ZsGreen cells were transfected with Wnt1, Wnt3A, and Wnt5A expression vectors, producing stably highly expressing cells." (PMID 37840014, 2023). "Consistent with previous reports, we found that Wnt5a is a potent activator of Wnt/PCP signaling that drives breast cancer cell migration." (PMID 37147680, 2023). "Collectively, these results show that WNT5A–IL-6–CCL2 are enriched in TNBC tumors that develop metastasis and that high expression of IL-6R or CCR2 is associated with breast cancer chemoresistance and recurrence." (PMID 37607007, 2023). "We performed hierarchical clustering of ROR1 with 24 EMT-related genes including the Hippo signaling pathway genes from the MSigDB database along with WNT5a, BMI1, BCL2, and GLI1 prompted by associations noted in prior studies on breast cancer or CLL." (PMID 37029329, 2023). "Remarkably, the inhibition of Wnt5a mediated by the disruption of Twist-BRD4 association suppresses CSC properties, reduces the invasion, and impairs tumorigenesis of basal breast cancer cells." (PMID 37492224, 2023). "Consistent with findings from mammalian development, Wnt5a stimulation phosphorylates Vangl2 at critical functional residues across a panel of breast cancer cell lines and loss of VANGL2 suppresses Dvl2 phosphorylation." (PMID 37147680, 2023). "A previous study showed that Wnt5A is required to mediate the effects of TGFβ on the mammary gland and breast cancer." (PMID 35053353, 2022). "Evidence for Wnt5A crosstalk with TGFβ1 was shown in mammary gland development and breast cancer, given that Wnt5A was required for TGF-β acting through antagonizing β-catenin, thereby limiting mammary gland morphogenesis." (PMID 35053353, 2022). "The expression and function of WNT5A regulated by ATBF1 was further investigated in breast cancer cell lines and clinical samples." (PMID 36476423, 2022).
breast carcinoma (continued). "After overall analysis of the most highly enriched KEGG pathways (pathways in cancer) and GO terms, WNT5A was found to be an attractive mechanism of ATBF1’s role in breast cancer, with the highest P value and fold change of all identified DEGs." (PMID 36476423, 2022). "In another study, YAP1 was found to regulate ROR1 expression, and Wnt5A/ROR1–YAP1/TAZ feedback loop was associated with cancer stem cell phenotype, tumor progression, metastasis, and, ultimately, drug resistance of breast cancer." (PMID 35053353, 2022). "In breast cancer, WNT5A from TAMs can induce the expression of MMP-7, resulting in matrix remodeling." (PMID 35847885, 2022). "It has also been shown in an independent study that ROR1 activation by WNT5A promotes breast cancer migration and metastasis." (PMID 36107918, 2022). "Expression levels of each positively correlated with expression of WNT5A/B and β-catenin, known downstream effectors of mammary tumors induced by AHR ligand activation." (PMID 36077068, 2022). "For this, we induced EMT in BT474 (HER2-high breast cancer cells) by treating the cells with an EMT-inducing supplement cocktail (containing Wnt-5a, TGF-β1, anti-human E-Cadherin antibody, anti-human sFRP1 antibody, and anti-human Dkk1 antibody) for 15 days." (PMID 34575017, 2021). "Wnt5a is reportedly overexpressed in approximately 30% of all breast cancer cases, and most Wnt5a-positive breast cancers are estrogen receptor (ER)-positive breast cancers." (PMID 34047951, 2021). "Wnt5a is upregulated in MDR uterus sarcoma and breast cancer cells, and is associated with hypomethylation of CpG islands of a Wnt5a intron sequence." (PMID 35582031, 2021). "Here, we confirmed that the increased stromal Wnt5a plays a crucial role in VEGF-independent angiogenesis in breast cancer." (PMID 33754039, 2021). "Downregulation of Daam1 or the knockdown of Wnt5a inhibits migration and invasion of breast cancer cells." (PMID 34178477, 2021). "A whole-transcriptome analysis of selectively retrieved engulfing breast cancer cells identified a gene signature of mesenchymal stem/stromal cell (MSC) engulfment consisting of Wnt5a, which enhanced distant metastasis." (PMID 33754039, 2021). "Previously, Wnt5a was mainly located in the TAMs of tumor stroma in breast cancer or basal cell carcinoma; Smith and colleagues consistently found that Wnt5a was mostly expressed in the tumor stroma of CRC, especially in TAMs." (PMID 32228612, 2020). "In thyroid, prostate, colon, and breast cancer, Wnt5A is suggested to have a tumor-suppressor role wherein reconstitution of Wnt5A impairs tumor metastasis by targeting cell motility and, therefore, is associated with a higher disease-free survival." (PMID 33126517, 2020). "WNT5A is involved in promoting breast cancer, and CDE is known to differentially modulate WNT signaling; thus, blockade of Rlip function should disrupt WNT signaling." (PMID 32498332, 2020). "WNT5A is a WNT inhibitory ligand, and Foxy-5, a WNT5A mimicking peptide, has been shown to reduce metastatic spread of WNT5A-low breast cancer cells in mouse models." (PMID 32391382, 2020). "WNT5a has also been reported to inhibit the migration and reverse EMT in colon and breast cancer cell lines which indicates that the effect of WNT5a is cell-type specific." (PMID 32546756, 2020). "Ykt6 knockdown in human Hek293T cells caused intracellular accumulation of overexpressed Wnt3A-GFP and reduced endogenous Wnt5A secretion from SK-BR-3 breast cancer cells." (PMID 32611603, 2020). "Macrophage Wnt5a was then, in turn, delivered to breast cancer cells via macrophage-derived MV and Exo, where it activated ß-catenin-independent Wnt signaling, leading to increased tumor invasion." (PMID 32731639, 2020). "Some members of the Wnt family, such as WNT5A, act as an antagonist of canonical Wnt signaling in some cancers such as colon cancer breast cancer and leukemia." (PMID 32824207, 2020).
breast carcinoma (continued). "Foxy-5, a Wnt5a-mimicking peptide, effectively reduced the metastasis in Wnt5a-low prostate cancer, breast cancer, etc.." (PMID 31480221, 2019). "Wnt5a is reported to have a tumor-suppressive function in colon cancer, neuroblastoma, breast carcinomas, and leukemia." (PMID 31480221, 2019). "In the present study, we found that Wnt5a induces ROR1 to associate with cortactin, which undergoes tyrosine phosphorylation in breast-cancer PDX cells or MCF7 cells transfected to express ROR1." (PMID 31667337, 2019). "The ROR1–PRD was essential for ROR1 to complex with cortactin and increase breast-cancer-cell migration in response to Wnt5a." (PMID 31667337, 2019). "In conclusion, the present study demonstrates a previously unrecognized ROR1/cortactin/ARHGEF1-dependent pathway leading to activation of RhoA in response to Wnt5a in breast-cancer cells." (PMID 31667337, 2019). "We believe that in the context of breast cancer progression, prolonged exposure of WNT5A is a more relevant physiological approach." (PMID 30171384, 2018). "We believe that to determine the role of Wnt5a expression in breast cancer, the level of Wnt5a expression in each of the breast cancer subtypes must first be determined." (PMID 29765514, 2018). "Ectopic expression of WNT5A protein suppresses breast cancer progression by increasing adhesion with concomitant decrease in cell migration and invasion." (PMID 30171384, 2018). "In the present section, we will discuss WNT5A signaling and how it can affect the functional responses of breast cancer cells with a focus on their migration and invasion." (PMID 30171384, 2018). "WNT5A expression has been studied in human breast cancer tissue by various investigators at both the transcriptional and protein level." (PMID 30171384, 2018). "In this study, we examine the significance of Wnt5a expression in breast cancer by determining the clinicopathologic characteristics of Wnt5a-positive breast cancers using Wnt5a immunohistochemical analysis of breast cancer specimens." (PMID 29765514, 2018). "WNT5A has been shown to control various signaling pathways involved in the regulation of breast cancer cell migration and invasion and thus, the metastatic process." (PMID 30171384, 2018). "Presence of the WNT5A ligand in human breast cancer correlates with increased disease-free survival and overall survival, indicating that WNT5A functions as a tumor suppressor." (PMID 30171384, 2018). "A distinct role for the small GTPase Cdc42 in WNT5A signaling in breast cancer cells has been demonstrated." (PMID 30171384, 2018). "We suspect that Wnt5a expression increases the malignancy of breast cancer by increasing the migratory capacity of cancer cells through the induction of ALCAM expression." (PMID 29765514, 2018). "It has been established that WNT5A expression in breast cancer tissue predicts a prolonged disease-free survival, whereas absence or low expression of WNT5A in breast cancer tissue is associated with a shorter disease-free survival." (PMID 30171384, 2018). "WNT5A triggers various downstream signaling pathways in breast cancer that primarily affect tumor cell migration and invasion." (PMID 30171384, 2018). "We observed that the migratory capacity of ER-positive breast cancer cells forced to express Wnt5a increased and the knockdown of Wnt5a led to a decrease in migratory capacity, whereas cell proliferation remained unchanged." (PMID 29765514, 2018). "Other studies report that Wnt5a expression increases the malignancy of breast cancer through activation of tumor-related macrophages or the promotion of cell migration." (PMID 29765514, 2018). "A positive correlation is reported between Wnt5a expression level and ER-positive breast cancer, as determined using breast cancer specimens." (PMID 29765514, 2018). "In the same study, the authors demonstrated that WNT5A signaling in breast cancer cells increases oxidative phosphorylation." (PMID 30171384, 2018).